F8 (coagulation factor VIII)
Diseases named in the same sentence as F8 in open-access papers (continued):
Sharing a sentence is not in itself a finding about the gene and the disease.
hemophilia A (continued). "Hemophilia A, the most frequent hereditary bleeding disorder, is an X-linked bleeding disorder due to deficiency in coagulation factor VIII (FVIII) that affects one individual in 5.000–10.000 newborn males." (PMID 34778454, 2021). "Hemophilia A (HA) is the most common X-linked inherited hemorrhagic disorder caused by mutations in the F8 gene, resulting in decreased coagulation factor VIII (FVIII) activity." (PMID 34485274, 2021). "Hemophilia A (HA) is an X-linked bleeding disorder due to inherited deficiency in coagulation factor VIII (FVIII) activity." (PMID 32425925, 2020). "In humans, Factor VIII (F8) deficiency leads to hemophilia A and F8 is largely synthesized and secreted by the liver sinusoidal endothelial cells (LSECs)." (PMID 33096636, 2020). "Hemophilia A (HA) is a F8 gene mutational disorder resulting in deficiency or dysfunctional FVIII protein." (PMID 32850803, 2020). "Hemophilia A (HA) is an X-linked bleeding disorder due to deficiencies in coagulation factor VIII (FVIII)." (PMID 32425925, 2020). "Hemophilia A (HA) is a bleeding disorder that is the result of a congenital deficiency of coagulation factor VIII (FVIII)." (PMID 32026972, 2020). "Hemophilia A (HA) is an X‐linked recessive bleeding disorder caused by pathogenic variants of the coagulation factor VIII gene (F8)." (PMID 32627361, 2020). "In the case of hemophilia A, the relationship between the development of anti-FVIII antibodies and the type of F8 mutation was recognized more than 20 years ago." (PMID 32351505, 2020). "Congenital haemophilia A (HA) is caused by deficiency of coagulation factor VIII (FVIII) activity, leading to spontaneous or traumatic bleeding events." (PMID 32717751, 2020). "Hemophilia is a genetic X-linked coagulative disorder caused by the deficiency of coagulation factor VIII (hemophilia A) or coagulation factor IX (hemophilia B)." (PMID 32581836, 2020). "The F8 protein, whose deficiency leads to hemophilia A, plays an important role in blood coagulation." (PMID 33096636, 2020). "Hemophilia A is an X-linked recessive bleeding disorder caused by various types of pathological defects in the factor VIII gene (F8/FVIII)." (PMID 33747028, 2020). "Loss-of-function variants in F8, which encodes coagulation factor VIII, cause hemophilia A, and microdeletions at Xq28 have been identified in patients with severe hemophilia A and moyamoya (SHAM) syndrome." (PMID 33193636, 2020). "Hemophilia A (HA) is caused by mutations in the gene encoding coagulation factor VIII (FVIII), with disease severity characterized by the resulting delayed plasma clotting time compared to normal human plasma." (PMID 32595650, 2020). "Hemophilia A (HA) is the most severe X-linked inherited bleeding disorder caused by hemizygous mutations in the factor 8 (F8) gene." (PMID 32026663, 2020). "Hemophilia A (HA) is an X‐linked recessive bleeding disorder caused by pathogenic variants of the coagulation factor VIII gene (F8, OMIM: 300841)." (PMID 32627361, 2020). "Hemophilia A (HA) is an X‐linked recessive bleeding disorder caused by mutations in the coagulation factor VIII gene (F8)." (PMID 32627361, 2020). "Hemophilia A and B are X-linked recessive disorders resulting from more than 3,000 known DNA variants in the genes encoding coagulation factor VIII (F8) and factor IX (F9), respectively." (PMID 32497118, 2020). "Haemophilia A (HA) is a rare X-linked bleeding disorder caused by a mutation in the gene coding for coagulation factor VIII (FVIII)." (PMID 33396748, 2020). "Hemophilia A is caused by mutations of the F8 gene encoding coagulation factor VIII, while hemophilia B develops due to mutations of the F9 gene, which encodes coagulation factor IX." (PMID 32189222, 2020). "Recombinant or plasma-derived FVIII is a lifesaving protein drug for hemophilia A (HA) patients, whose F8 gene mutations result in either a complete lack of endogenous FVIII or in a circulating dysfunctional FVIII." (PMID 31998296, 2019).
hemophilia A (continued). "The present study investigates the relationship between genetic factors and FVIII inhibitor development in severe hemophilia A patients, together with F8 mutation type, a family history of inhibitors and FVIII product type." (PMID 31194850, 2019). "Hemophilia A is a monogenic disease with a blood clotting factor VIII (FVIII) deficiency caused by mutation in the factor VIII (F8) gene." (PMID 31727959, 2019). "The F8 mutation type and a family history of FVIII inhibitors were confirmed as being associated with inhibitor development in severe hemophilia A patients." (PMID 31194850, 2019). "Congenital hemophilia is a life-long, X-linked hereditary bleeding disorder caused by the deficiency of coagulation factor VIII (FVIII) (hemophilia A) or factor IX (FIX) (hemophilia B)." (PMID 30413215, 2018). "Hemophilia A is an X-linked bleeding disorder caused by a deficiency in coagulation factor VIII (fVIII)." (PMID 29552578, 2018). "Hemophilia A is a congenital bleeding disorder caused by a deficiency of blood coagulation factor VIII (FVIII)." (PMID 30873482, 2018). "Hemophilia A (HA) is an X-linked recessive blood disorder characterized by decreased levels of coagulation factor VIII (FVIII)." (PMID 30246038, 2018). "Haemophilia-A is an X-linked recessive disorder in humans caused by mutations in the coagulation factor VIII (F8) gene, resulting in dysfunction of blood coagulation." (PMID 29208927, 2017). "One disease model used in our lab to study the therapeutic potential of antigen-specific Tregs is hemophilia A. Hemophilia A is an X-linked bleeding disorder caused by mutations in the factor 8 (F8) gene, which encodes the blood coagulation protein, FVIII." (PMID 28983300, 2017). "We have developed a porcine model of human haemophilia A (haemophilia-A pigs) by nuclear transfer cloning from foetal fibroblasts after disruption of the X-linked coagulation factor VIII (F8) gene." (PMID 29208927, 2017). "Hemophilia A is an X-linked recessive bleeding disorder caused by a quantitative or qualitative deficiency of coagulation factor VIII (FVIII)." (PMID 28327546, 2017). "The demand for IgG for treating immune deficiencies and coagulation factor VIII for hemophilia A determines how to design the plasma fractionation industry in terms of capacity." (PMID 28959338, 2016). "Hemophilia A is a hereditary disorder resulting in deficient levels of plasma coagulation factor VIII (FVIII) and lifelong bleeding manifestations, particularly repeated hemarthroses leading to permanent joint damage." (PMID 27158500, 2016). "Hemophilia is a recessive X-linked hereditary disorder characterized by a deficiency of coagulation factor VIII (FVIII) in hemophilia A or factor IX (FIX) in hemophilia B, and caused by mutations in the genes coding for such factors." (PMID 27114871, 2016). "Hemophilia A is an X-linked bleeding disorder resulting from dysfunctional blood coagulation factor VIII (fVIII), affecting 1 in 5,000 males worldwide." (PMID 25775247, 2015). "Hemophilia A is an X-linked bleeding disorder caused by the deficiency of coagulation Factor VIII and is currently treated by intravenous injection of replacement factor VIII, either as on-demand or prophylaxis therapy." (PMID 25905473, 2015). "Hemophilia A is a congenital bleeding disorder caused by a deficiency of procoagulation Factor VIII (FVIII)." (PMID 25126862, 2014). "Hemophilia A is an X-linked congenital bleeding disorder characterized by a deficiency in functional coagulation factor VIII (fVIII) in the blood compartment." (PMID 26015976, 2014). "Hemophilia A is a deficiency in coagulation factor VIII (FVIII) and hemophilia B is a deficiency in coagulation factor IX (FIX)." (PMID 24883229, 2013). "Haemophilia is a monogenic disease due to mutations in the gene encoding for coagulation factor VIII (FVIII; haemophilia A) or factor IX (FIX; haemophilia B)." (PMID 24106222, 2013).
hemophilia A (continued). "Hemophilia A is an inherited bleeding disorder caused by a deficiency of coagulation factor VIII (FVIII)." (PMID 24358271, 2013). "Hemophilia A (HA) is an X-linked genetic disorder that results in deficiencies of coagulation factor VIII (FVIII)." (PMID 24236042, 2013). "Acquired hemophilia A is a rare, but devastating bleeding disorder caused by spontaneous development of autoantibodies directed against coagulation factor VIII." (PMID 24385759, 2013). "Hemophilia A is an X linked recessive hemorrhagic disorder caused by mutations in the F8 gene that lead to qualitative and/or quantitative deficiencies of coagulation factor VIII (FVIII)." (PMID 22883072, 2012). "Hemophilia A is a common X chromosome-linked genetic bleeding disorder caused by abnormalities in the coagulation factor VIII gene (F8)." (PMID 23209578, 2012). "This suggests that the F8 KO pig is a subhuman animal model of severe hemophilia A for the study of upcoming therapeutic factors, such novel FVIII variants." (PMID 23209578, 2012). "Hemophilia A is an inherited X-linked bleeding disorder caused by abnormalities in the coagulation factor VIII (FVIII) gene (F8)." (PMID 23209578, 2012). "Hemophilia A mice generated by targeted ablation of mouse F8 have been the mainstay for assessment of hemophilia A gene therapy and evaluation of FVIII variants." (PMID 23209578, 2012). "Most of the mutations in haemophilias leads to insufficient activity of the tenase complex, brought about either by a deficiency of coagulation factor VIII cofactor activity (haemophilia A) or coagulation factor IX enzyme activity (haemophilia B)." (PMID 22423892, 2012). "Hemophilia A is a bleeding disorder caused by a deficient coagulation factor VIII (FVIII) that affects one in 5,000 to 10,000 males." (PMID 22115125, 2011). "Coagulation factor VIII (FVIII) deficiency leads to haemophilia A. Conversely, elevated plasma levels are a strong predictor of recurrent venous thromboemboli and pulmonary hypertension phenotypes in which in situ thromboses are implicated." (PMID 20174619, 2010). "The bleeding disorder haemophilia A is caused by defects in the gene encoding coagulation factor VIII and affects 1–2 in 10,000 male births." (PMID 19707594, 2009). "Hemophilia A(HA) is caused by mutations in the F8 gene, leading to a deficiency or dysfunctional III protein, an essential cofactor in the factor X activation complex." (PMID 18565236, 2008). "Hemophilia A is a congenital coagulation disorder caused by X-linked recessive inheritance, where the coagulation reaction is delayed due to decreased activity of coagulation factor VIII (FVIII), resulting in symptoms of bleeding." (PMID 40438813, 2025). "Hemophilia A (HA) is caused by mutations in coagulation factor VIII (FVIII)." (PMID 39762408, 2025). "In addition to MPS VI, AAV-HITI efficacy was assessed in a mouse model of hemophilia A (HemA), the most common X-linked bleeding disorder caused by mutations in the F8 gene." (PMID 38897206, 2024). "Factor VIII (F8) is a blood coagulation protein prearranged in six domains, and its deficiency causes hemophilia A. To fashion functional F8 therapeutics, development of a recombinant F8 (rF8) domain is essential not only for F8 substitution, but also to decipher the F8-related mechanisms." (PMID 37109652, 2023). "Hemophilia A (coagulation factor VIII(FVIII) deficiency), which is caused by the mutation in F8 gene and leads to abnormal production or function of FVIII protein, is the most common clinical hereditary hemorrhagic disease, with an incidence of about 1/5,000 in males." (PMID 36845383, 2023). "Deficiency of coagulation factor VIII in hemophilia A disrupts clotting and prolongs bleeding." (PMID 37264009, 2023). "Haemophilia A is an inherited disease caused by a defect in the gene located on the long arm of the X chromosome, causing a qualitative or quantitative deficiency of coagulation factor VIII." (PMID 36810557, 2023).
hemophilia A (continued). "Bleeding from hemophilia, a bleeding disorder caused by deficiency of coagulation factor VIII (hemophilia A) or factor IX (hemophilia B), could be life‐threatening without prompt interventions." (PMID 37206230, 2023). "Hemophilia A is a rare hereditary bleeding disorder caused by a deficiency of coagulation factor VIII (FVIII) and characterized by repeated and prolonged bleeding into muscles and joints that lead to pain, physical limitations and a negative impact on health-related quality of life (HRQoL)." (PMID 37410717, 2023). "Hemophilia A is an X-linked recessive disorder caused by insufficiency of coagulation factor VIII." (PMID 35282827, 2022). "Acquired hemophilia A is a disorder caused by autoantibodies against coagulation factor VIII that may present with severe bleeding." (PMID 35501873, 2022). "Although prophylactic treatment with coagulation factor VIII (FVIII) concentrate is preferred to prevent bleeding and joint damage in children with severe hemophilia, there are still several risk factors for the treatment of hemophilia A." (PMID 36294464, 2022). "Hemophilia A (HA) is caused by mutations in the coagulation factor VIII (FVIII) gene (F8)." (PMID 35054807, 2022). "Hemophilia is an inherited bleeding disorder in which the hemostatic defect results from deficiency of coagulation factor VIII (FVIII) in hemophilia A or factor IX (FIX) in hemophilia B. Traditional treatments for hemophilia have largely worked by directly replacing the missing coagulation factor." (PMID 36297304, 2022). "Acquired hemophilia A is a rare coagulopathy caused by inhibitors of blood coagulation factor VIII." (PMID 33583426, 2021). "Hemophilia A is a bleeding disease caused by loss of coagulation factor VIII (FVIII) function." (PMID 34572302, 2021). "Hemophilia A (HA) is an X chromosome-linked bleeding disorder that is associated with mutations in the Factor 8 (F8) gene leading to either reduced expression or production of a dysfunctional FVIII protein." (PMID 32850803, 2020). "Severe hemophilia A results from major deletions or inversions in the F8 gene, such that these individual have less than 1% FVIII activity; mild hemophilia can occur with missense mutations, for example, that also lead to significantly reduced clotting efficacy." (PMID 29181011, 2017). "Hemophilia A is an X-linked bleeding disorder caused by mutations in the FVIII (F8) gene." (PMID 29181011, 2017). "For example, at least five reported cases of hemophilia A have been linked to germline MEIs that disrupted the coagulation factor VIII (F8) gene, and another six cases of hemophilia B have been linked to germline MEIs that disrupted the coagulation factor IX (F9) gene." (PMID 28855259, 2017). "Human factor VIII (FVIII) functions as a cofactor for activated factor IX, and mutations in the FVIII gene (F8) result in hemophilia A. FVIII in plasma is proteolyzed and/or pinocytosed unless it is protected by non-covalent binding to soluble forms of von Willebrand factor (VWF) multimers." (PMID 26473492, 2015). "Hemophilia A is caused by an X-linked inherited dysfunction of coagulation factor VIII (FVIII)." (PMID 23468998, 2013). "Hemophilia A is a bleeding disorder caused by deficiency in coagulation factor VIII." (PMID 22115125, 2011). "Because HEK293TloxF8 cells carry the F8 gene in the wild type orientation, recombinase expression could potentially invert the loxF8 locus into the disease orientation as it is present in patients with severe Hemophilia A caused by the F8 int1h inversion." (PMID 35058465, 2022). "Haemophilia A and B are X chromosome‐linked conditions that are often mistakenly thought to affect males with females being carriers; however, a range of phenotypes are observed in females who have one copy of an abnormal gene for coagulation factor VIII (haemophilia A) or factor IX (haemophilia B)." (PMID 30924538, 2019).
hemophilia A (continued). "BMN-270 Phase I/II clinical trial by BioMarin Pharmaceutical was started in 2020 and subsequently showed promising preliminary results in the treatment hemophilia A patients with pre-existing immunity to coagulation factor VIII (FVIII)." (PMID 41511298, 2025). "Haemophilia A and B, caused by the deficiency of coagulation factor VIII (FVIII) and FIX, respectively, predispose individuals to spontaneous bleeding in the musculoskeletal system and consequent joint damage, often necessitating joint replacement." (PMID 41069331, 2025). "Hemophilia A and B are X-linked monogenic disorders caused by F8/F9 gene variants characterized by low levels of clotting factor VIII (FVIII)/factor IX (FIX), respectively." (PMID 40161079, 2025). "Acquired hemophilia A (AHA) is a rare, life-threatening bleeding disorder caused by the development of autoantibodies against coagulation factor VIII." (PMID 41220543, 2025). "Acquired hemophilia A (AHA) is a rare and life-threatening bleeding disorder caused by inhibitors against coagulation factor VIII (FVIII)." (PMID 40861746, 2025). "Cases of hemophilia A, which is characterized by reduced coagulation factor VIII, have been reported but cases involving diminished factors VII, XI, or XII have not been reported." (PMID 40130099, 2025). "For example, caution is required for patients with hemophilia A due to the temperature-sensitive degradation of coagulation factor VIII." (PMID 41255764, 2025). "The severity of hemophilia A (HA) is determined by the residual FVIII activities of circulating endogenous FVIII, which result from mutations and deletions in the FVIII-encoding F8 gene." (PMID 38510258, 2024). "The disorder manifests in two primary forms: hemophilia A, caused by reduced levels of coagulation factor VIII (FVIII), and hemophilia B (also known as Christmas disease), caused by reduced levels of coagulation factor IX (FIX)." (PMID 39337384, 2024). "The currently approved gene therapy for the inherited bleeding disease hemophilia A is limited by a decreasing trend in the reconstituted coagulation factor VIII (FVIII) activity and its expected duration is in the range of 5–10 years in adults." (PMID 38684862, 2024). "Hemophilia is an X-linked inherited disorder characterized by a chronic, life-threatening condition caused by low levels of factor IX (FIX) in hemophilia B and coagulation factor VIII (FVIII) in hemophilia A." (PMID 39728001, 2024). "Hemophilia A (HA) is an X-linked recessive bleeding disorder caused by mutations in the F8 gene, resulting in deficient or dysfunctional factor VIII (FVIII)." (PMID 39125936, 2024). "Hemophilia A and B are hereditary bleeding disorders characterized by deficiencies in coagulation factor VIII (FVIII) and factor IX (FIX), respectively." (PMID 37176534, 2023). "Hemophilia is an X-linked congenital hemorrhagic disorder caused by F8 or F9 single gene mutations that cause secretion insufficiency of coagulation factor VIII (FVIII; Hemophilia A) Or clotting factor IX (FIX; Hemophilia B)." (PMID 38145048, 2023). "Hemophilia-A (HA) is caused by heterogeneous loss-of-function factor (F)VIII gene (F8)-mutations and deficiencies in plasma-FVIII-activity that impair intrinsic-pathway-mediated coagulation-amplification." (PMID 37886476, 2023). "Hemophilia A (HA) is an inherited X-linked bleeding disorder, caused by the deficiency of coagulation factor VIII (FVIII), with variable clinical phenotypes [...]." (PMID 36835904, 2023). "Hemophilia A (HA, OMIM#306700) is an X-linked recessive bleeding disorder caused by the defects in the F8 gene, which encodes coagulation factor VIII (FVIII)." (PMID 36845383, 2023). "This is a strategy whose objective is to decrease the immune response to the presence of FVIII in haemophilia A through frequent and intensive exposure to coagulation factor VIII." (PMID 36810557, 2023).